RPL23AP64 (ribosomal protein L23a pseudogene 64)
Gene: Processed pseudogene on chromosome 11 (119,003,012 to 119,003,446, reverse strand). Ensembl gene ENSG00000240970.
Diseases named in the same sentence as RPL23AP64 in open-access papers:
RPL23AP64 is named in the same sentence as 1 disease in open-access papers, as found by Europe PMC text mining. Sharing a sentence is not in itself a finding about the gene and the disease.
RPL23AP64 shares sentences with these, for which no sentence is quoted: lung carcinoma (1 paper).